LRR1 (leucine rich repeat protein 1)
Description:
Substrate recognition subunit of an ECS (Elongin BC-CUL2/5-SOCS-box protein) E3 ubiquitin-protein ligase complex which mediates the ubiquitination and subsequent proteasomal degradation of target proteins. ECS(LRR1) ubiquitinates MCM7 and promotes CMG replisome disassembly by VCP and chromatin extraction during S-phase (By similarity). May negatively regulate the 4-1BB-mediated signaling cascades which result in the activation of NK-kappaB and JNK1.
Synonyms: LRR-1; PPIL5; 4-1BBLRR; MGC20689
Tractability: Small molecule: a structure with a bound ligand is known. PROTAC: ubiquitination databases record sites on it.
Gene: Protein-coding gene on chromosome 14 (49,598,761 to 49,614,672, forward strand). Ensembl gene ENSG00000165501.
Subcellular location: Nucleus
Subcellular location (Human Protein Atlas): Nuclear membrane; Nucleoplasm; Vesicles
Pathways (Reactome):
Immune System: Antigen processing: Ubiquitination & Proteasome degradation
Metabolism of proteins: Neddylation
Gene Ontology:
Molecular function: protein binding
Biological process: intracellular signal transduction; negative regulation of DNA-templated DNA replication; protein ubiquitination
Cellular component: Cul2-RING ubiquitin ligase complex; nucleus; cytosol
Genetic constraint (gnomAD): Loss-of-function variants: 28 observed, 30.43 expected, observed/expected ratio (o/e) 0.92, 90% interval 0.68 to 1.26. The upper end of that interval is the gene's LOEUF score, 1.26, which puts it in group 5 of 6, group 1 being the genes least tolerant of losing a copy. Missense variants: 484 observed, 501.89 expected, observed/expected ratio (o/e) 0.96, 90% interval 0.89 to 1.04. Synonymous variants: 178 observed, 186.46 expected, observed/expected ratio (o/e) 0.95, 90% interval 0.84 to 1.08.
Homologues: Orthologues: chimpanzee LRR1 (99% identical), macaque LRR1 (96% identical), pig LRR1 (90% identical), rabbit LRR1 (90% identical), dog LRR1 (87% identical), guinea pig LRR1 (82% identical), mouse Lrr1 (79% identical), rat Lrr1 (79% identical), tropical clawed frog lrr1 (63% identical), zebrafish lrr1 (42% identical), Drosophila melanogaster Lrr47 (27% identical).
Diseases named in the same sentence as LRR1 in open-access papers:
LRR1 is named in the same sentence as 8 diseases in open-access papers, as found by Europe PMC text mining. Sharing a sentence is not in itself a finding about the gene and the disease. The quoted sentences say what the papers report.
depression (1 paper, 2022). "A previous study showed that LRR1 regulates 4-1BB-mediated signaling cascades, which activate NF-кB, and NF-кB could affect depression." (PMID 36520780, 2022).
liver cancer (1 paper, 2022). An epithelial or non-epithelial malignant neoplasm that arises from the liver. "Leucine-rich repeat protein 1 (LRR1) suppresses activation of NF-Kappa B. High LRR1 expression increases the mortality of liver cancer and renal cancer." (PMID 35158795, 2022).
uveitis (1 paper, 2020). An inflammatory process affecting a part of or the entire uvea. "The results suggested that the upregulation of LRR-1 was involved in endotoxin tolerance in uveitis." (PMID 32671118, 2020). "Therefore, this study attempted to investigate whether CSF-1 and LRR-1 are involved in endotoxin tolerance in uveitis through the TLR4 pathway and their exact mechanisms." (PMID 32671118, 2020).
infection (3 papers, 2017 to 2023). The state of being infected such as from the introduction of a foreign agent such as serum, vaccine, antigenic substance or organism. "A significant decrease ( approx. 70%) in the number of oocysts was observed in LRR1 KO parasites at day 9 post infection, and oocysts at this stage of development were smaller in size." (PMID 35920043, 2022). "The LRR1 ortholog of pepper, CaLRR1, which is induced upon infection with Xanthomonas campestris pv." (PMID 28534133, 2017). "In a previous work, the genes LRR1 and LRR2 were induced in tomato plants during infection by Pst DC3000, while the expression of miR482 was downregulated." (PMID 36903899, 2023).
tumor (2 papers, 2024). "The neoepitopes ISSKFKSKR (DDX47) and IEIEDTFETLW (TGFBI) corresponded to category V, and HSTLQKSLW (LRR1) together with KLRKKQNER (SLFN12) neoepitopes corresponded to category TV, being expressed both in VACCIMEL and patient #032’s tumor." (PMID 39840067, 2024).
LRR1 also shares sentences with these, for which no sentence is quoted: nematode infection (1 paper); renal carcinoma (1); schizophrenia (1).